SRY (sex determining region Y)
Description:
Transcriptional regulator that controls a genetic switch in male development. It is necessary and sufficient for initiating male sex determination by directing the development of supporting cell precursors (pre-Sertoli cells) as Sertoli rather than granulosa cells. Involved in different aspects of gene regulation including promoter activation or repression. Binds to the DNA consensus sequence 5'- [AT]AACAA[AT]-3'. SRY HMG box recognizes DNA by partial intercalation in the minor groove and promotes DNA bending. Also involved in pre-mRNA splicing. In male adult brain involved in the maintenance of motor functions of dopaminergic neurons (By similarity).
Synonyms: TDF; SRXX1; SRXY1; TDY
Tractability: Small molecule: a structure with a bound ligand is known; it has a binding pocket of medium quality.
Gene: Protein-coding gene on chromosome Y (2,786,855 to 2,787,682, reverse strand). Ensembl gene ENSG00000184895.
Subcellular location: Nucleus speckle; Cytoplasm; Nucleus
Pathways (Reactome):
Developmental Biology: Transcriptional regulation of testis differentiation
Signal Transduction: Deactivation of the beta-catenin transactivating complex
Gene Ontology:
Molecular function: DNA binding; DNA-binding transcription factor activity, RNA polymerase II-specific; DNA-binding transcription factor binding; protein binding; DNA-binding transcription activator activity, RNA polymerase II-specific; RNA polymerase II cis-regulatory region sequence-specific DNA binding; DNA-binding transcription factor activity
Biological process: positive regulation of DNA-templated transcription; positive regulation of gene expression; positive regulation of male gonad development; cell differentiation; male sex determination; positive regulation of transcription by RNA polymerase II; regulation of transcription by RNA polymerase II
Cellular component: cytoplasm; nuclear speck; nucleus; chromatin; nucleoplasm
Homologues: Orthologues: chimpanzee SRY (97% identical), macaque SRY (89% identical), pig SRY (58% identical), dog SRY (56% identical), zebrafish sox19a (37% identical), rat Sry (35% identical), rat Sry3 (35% identical), rat Sry3A (35% identical), rat Sry3B1 (35% identical), rat Sry3C (35% identical), rat Sry3b2 (35% identical), rat Sry2 (35% identical), and 11 more. Paralogues in human: SOX3 (39% identical), SOX2 (37% identical), SOX1 (37% identical), SOX21 (33% identical), SOX14 (32% identical), SOX15 (31% identical), SOX7 (28% identical), SOX6 (27% identical), SOX9 (27% identical), SOX17 (27% identical), SOX30 (26% identical), SOX11 (26% identical), and 8 more.
Diseases named in the same sentence as SRY in open-access papers:
SRY is named in the same sentence as 102 diseases in open-access papers, as found by Europe PMC text mining. Sharing a sentence is not in itself a finding about the gene and the disease. The quoted sentences say what the papers report.
Swyer syndrome (19 papers, 2007 to 2026). "One patient had normal mullerian structures and 46XY karyotype, a typical presentation of Swyer syndrome in which there is mutation and deletion in the SRY gene on the Y chromosome." (PMID 40103879, 2025). "In sheep, a mutation on the SRY promotor has been shown to lead to hermaphrodism, and, in cattle, deletion of SRY was associated with Swyer Syndrome-like condition in 7 out of 8 animals." (PMID 40218369, 2025). "Accordingly, in the human SRY translocation to the X-chromosome induces XX-maleness and inactivating mutations of SRY lead to 46,XY gonadal dysgenesis, also called Swyer syndrome." (PMID 38840820, 2023). "For instance, changes in the NLS sequence of the SRY gene cause Swyer syndrome because of reduced nuclear translocation of the protein." (PMID 36994096, 2023). "After the evaluation, she was diagnosed with Swyer syndrome due to a mutation in the SRY gene, leading to failure of testicular development." (PMID 36158407, 2022). "This and our companion study pertain to Swyer syndrome: 46, XY gonadal dysgenesis due to mutations in SRY." (PMID 36568077, 2022). "Most cases of human male-to-female sex reversal syndrome (Swyer syndrome) are associated with mutations in or dysfunctions of the SRY gene which are mainly located within the HMG domain." (PMID 33443157, 2021). "Although CAIS is the most common form, resulting in feminization of a 46, XY fetus, there are other syndromes one must consider: SRY gene mutations, 5-α reductase deficiency, Swyer syndrome, 17-α-hydroxylase deficiency, and Smith-Lemli-Optiz syndrome." (PMID 34670306, 2021). "In 10–15% of 46,XY gonadal dysgenesis cases (i.e., Swyer syndrome), SRY mutations, residing in the HMG (High Mobility Group) domain, are found to affect nuclear transport or binding to and bending of DNA." (PMID 22815844, 2012). "The patient described here was initially diagnosed as a 46,XY DSD complete gonadal dysgenesis and a (until now unclassified) mutation in SRY was found (i.e. Swyer syndrome), associated with GB and dysgerminoma." (PMID 22815844, 2012). "Swyer syndrome may be caused by SRY mutation (10%–15%), FTHL17, STARD8, SOX9, MAP3K1, NR5A1, and desert hedgehog gene (DHH) mutation as well as other unidentified genes." (PMID 41163677, 2025). "However, mutations and deletions in SRY can be detected in only 10-20% of patients with Swyer syndrome." (PMID 26316442, 2015). "Similar to Swyer syndrome, partial gonadal dysgenesis can result from mutations of the SRY gene." (PMID 24278745, 2012). "Approximately 15% of Swyer syndrome cases result from SRY point mutations, another 15% from SRY deletions caused by aberrant X/Y recombination, while nearly 70% of all cases have unidentified causes, which may be due to mutations in other testis‐determining genes." (PMID 41551439, 2026). "Humans with Swyer syndrome display gonadal dysgenesis characterized by streak gonads and infertility, which is comparable to our findings in SRY-KO pigs." (PMID 33443157, 2021). "Mutations in the SRY gene are identified in approximately 15% 46, XY females (Swyer syndrome); translocation of the SRY gene to the X chromosome is reported in a subset of 46, XX males." (PMID 29454353, 2018). "If SRY does mediate attention/impulsivity phenotypes, we might further speculate that females with Swyer syndrome who possess a 46,XY chromosomal constitution but who commonly lack a functional SRY gene, might display abnormalities in these domains." (PMID 21983394, 2012). "For some, but not all, people with Swyer syndrome, the underlying etiology is a mutation or deletion of the SRY gene necessary for differentiation of a bipotential gonad into a testis." (PMID 24278745, 2012).
gonadoblastoma (11 papers, 2010 to 2023). A mixed germ cell/sex cord-stromal tumor characterized by the presence of large germ cells which resemble seminoma cells and small cells which resemble Sertoli or granulosa cells. "The risk of developing gonadoblastoma among individuals with SRY-positive Turner syndrome remains controversial, according to the published literature." (PMID 35935368, 2022). "Risk of gonadoblastoma is high when the early stage of Sertoli cell differentiation is disrupted by mutations in SRY, WT1, SOX9, DMRT1, FOG2/GATA4, FGF9 etc.." (PMID 28825592, 2018). "Patients with SRY gene require special attention since the presence of Y chromosome correlates with 10–30% risk of developing gonadoblastoma or dysgerminoma later in life." (PMID 23984076, 2013). "It is widely recognized that dysgenetic gonads, in some cases related to SRY mutations develop gonadoblastoma only in case GBY region is present in the genome." (PMID 20849656, 2010). "TS with mosaic 45, X/46, XY karyotype comprises a phenotype spectrum of female (10-15%) having mutated SRY and an increased risk for developing of gonadoblastoma or dysgerminoma." (PMID 20849656, 2010). "They suggest that the presence of the mutated SRY gene might play a role in the development of gonadoblastoma and seminoma, being the precursor lesion and the invasive component of GCC respectively." (PMID 23157850, 2012). "Our results suggest that lack of a second sex chromosome in majority cells of the patient may have triggered the short stature and primary infertility, and the mutated SRY protein may be associated with the development of gonadoblastoma." (PMID 20849656, 2010). "Moreover, SRY positivity in a 46,XX patient, a 46,XY karyotype, an intra-abdominal gonad, and the age of patient at the time of diagnosis are predictive risk factors for the development of gonadoblastoma and/or dysgerminoma in ovotesticular DSD." (PMID 27087521, 2016). "Ectopic expression of SRY, as a part of the Y chromosome in case 1 diagnosed with 46, XX ovotesticular DSD is the main risk factor for the development of gonadoblastoma." (PMID 27087521, 2016). "It is important to rule out the presence of the SRY gene (sex-determining region Y) which is responsible for the development of the male sex and increases the risk of gonadoblastoma in residual gonads." (PMID 34256805, 2021). "Here, additional dysgerminoma and gonadoblastoma in a patient with 46,XY ovotesticular DSD and SRY positivity in a patient with 46,XX ovotesticular DSD are reported." (PMID 27087521, 2016).
Infertility (11 papers, 2010 to 2023). "Additionally, ICSI patients have higher risk to harbour infertility-predisposing mutations, including mutations in the SRY gene." (PMID 35123446, 2022). "In contrast, a translocation of the SRY gene on the X chromosome or autosomes in 46,XX individuals is associated with a male genital development but hypogonadism and infertility, indicating that SRY is necessary but not sufficient for testis development." (PMID 38840815, 2023). "Taken together, our observations provide the first evidence that deletion of two Sp1-binding sites located in the 5′ region of SRY induces sex reversal in rabbits and that a reduced number of ovulated oocytes is responsible for the infertility of sex-reversed rabbits." (PMID 28445127, 2017). "Patients with SRY-positive, which always translocates to the X chromosome or to an autosome, are usually more likely to have a normal male phenotype at birth and are referred for infertility treatment after puberty." (PMID 25529318, 2014). "So, it is difficult to find SRY+ male DSD patients before puberty, who are often incidentally found by chromosome check for infertility or poor testicle development." (PMID 31336995, 2019).
glioma (8 papers, 2018 to 2024). A benign or malignant brain and spinal cord tumor that arises from glial cells (astrocytes, oligodendrocytes, ependymal cells). "In order to determine the presence of glioma stem cells, we also stained for SRY (sex determining region Y)-box 2 (SOX2)." (PMID 39196480, 2024). "In addition, we identified a set of co-expressed genes enriched for SRY targets that exhibits differential survival among low-grade glioma patients on temozolomide, and previous studies have shown a link between the SRY pathway and sensitivity to temozolomide." (PMID 33654134, 2021). "Considering that SRY mainly depends male sex, we identified SOX10 as a biomarker of glioma prognosis." (PMID 36524115, 2022). "Finally, we compared the relative SRY mRNA expression between GBM and lower grade gliomas (LGG grade II and III; mean age 37.9 years, range: 14–70 years) from TCGA." (PMID 33807423, 2021).
hepatocellular carcinoma (8 papers, 2018 to 2025). A malignant tumor that arises from hepatocytes. "Surprisingly, these pathways were enriched in the low SRY expression group, contradicting findings from the hepatocellular carcinoma studies." (PMID 33807423, 2021). "Studied mainly for its sex-determining properties, SRY recently gained an unexpected label of a potential oncogene in hepatocellular carcinoma." (PMID 33807423, 2021). "Under increased substrate stiffness, hepatocellular carcinoma cells (HCC) demonstrate enhanced features of stemness and upregulation of Akt, mTOR, 4E-BP, and SRY (sex-determining region Y)-box 2 (SOX2) phosphorylation." (PMID 35163745, 2022). "In this study, we assessed the power of sex-determining region Y (SRY)-related high-mobility group (HMG)-box 4(SOX4) gene to predict the clinical course of hepatocellular carcinoma (HCC)." (PMID 33995626, 2021). "These cells express the CCA markers SRY (Sex Determining Region Y)-Box 9 (SOX9), cytokeratin (CK)-7 and 19 but lack hepatocyte nuclear factor 4 alpha and alpha-smooth muscle actin, markers of hepatocellular carcinoma and cancer-associated fibroblasts, respectively." (PMID 29464042, 2018). "SRY (through its downstream factor SOX9) impairs the differentiation of liver progenitor cells into hepatocytes, contributing to chronic liver inflammation and fibrosis, thereby promoting hepatocellular carcinoma (HCC) progression." (PMID 40438106, 2025). "Additionally, SRY, via its downstream target SOX9, promotes hepatocellular carcinoma (HCC) progression by upregulating CXCL5 expression and activating the CXCL5/CXCR2 signaling axis, thereby enhancing tumor cell proliferation and invasion." (PMID 40438106, 2025).
Turner syndrome (8 papers, 2008 to 2025). Turner syndrome is a chromosomal disorder associated with the complete or partial absence of an X chromosome. "Generally, in clinical practice, SRY-positive Turner syndrome is in the moderate-risk group of gonadal tumors, and prophylactic bilateral gonadectomy is recommended." (PMID 35935368, 2022). "Interestingly, the same SRY-S18N mutation has also been isolated in a separate individual who presented with Turner syndrome and Y chromosome mosaicism (Ulrich Turner Syndrome)." (PMID 21412441, 2011). "A 45,X0 and a 46,XY cell line containing the SRY gene were observed in a culture of fibroblasts from amniotic fluid, indicating a mosaic karyotype with characteristics that direct male development and elements of Turner syndrome." (PMID 40843888, 2025). "Understanding the duplication events in the rat may help to explain duplications of SRY seen in humans exposed to radiation or with Turner syndrome." (PMID 24228692, 2013). "Copy number polymorphism of the SRY and DAZ genes in the Turner Syndrome patients." (PMID 19030103, 2008). "In this study, in SRY-positive girls with Turner syndrome without signs of virilization, the rate of tumor occurrence was relatively low (1/10, 10%), which is consistent with findings in most of the published literature." (PMID 35935368, 2022).
Azoospermia (7 papers, 2020 to 2024). Absence of any measurable level of sperm,whereby spermatozoa cannot be observed even after centrifugation of the semen pellet. "The study was conducted before the detection of SRY and the AZF region, but the SRY gene was most likely intact in this man, who had azoospermia." (PMID 38093178, 2023). "This study conduct on23 idiopathic azoospermia men and 5 fertile men as the control group for analyzing the DAZ, RBMY1, USP9Y, protamine-2, SRY, and actin gene expression." (PMID 33349804, 2020). "The clinical manifestations of 46, XX male sex reversal syndrome vary with the presence or absence of SRY gene, involving some common features such as small testes, azoospermia, oligospermia, the differences in male phenotype, external genitalia, and female breast development." (PMID 35846903, 2022).
dysgerminoma (6 papers, 2007 to 2023). A malignant germ cell tumor characterized by the presence of a monotonous primitive germ cell population. "In conclusion, we identified a novel point mutation, 224G>T (R75M), in SRY coding region that causes a 46, XY complete gonadal dysgenesis with bilateral dysgerminoma." (PMID 28030592, 2016). "Here we report a de novo mutation 224G>T (R75M) in SRY associated with a phenotypic female, 46, XY karyotype and dysgerminoma." (PMID 28030592, 2016).
gonadal dysgenesis (6 papers, 2007 to 2025). A congenital disorder characterized by the presence of extremely hypoplastic gonads preventing the development of secondary sex characteristics. "Mutations in NR5A1, DMRT1, and MAP3K1 are other leading causes, but together with mutations in the SRY gene, they explain less than 40% of all non‐syndromic forms of 46 XY gonadal dysgenesis." (PMID 40747867, 2025). "Of these, two had gonadal dysgenesis (case 5 with a mutation in the SRY gene and case 6) and also had low or undetectable concentrations of inhibin B and AMH." (PMID 27899089, 2016). "The etiology of 46 XY gonadal dysgenesis is though to be a short arm Y chromosome deletion involving SRY, a mutation in other genes that leads to inhibition of SRY function or mutation of SRY function." (PMID 17587461, 2007). "Given that it has been estimated that up to 70% of such cases of gonadal dysgenesis in the human population remain unaccounted for by mutations in known sex determining genes such as SRY and SOX9, such a gene-driven approach to identifying candidates is well motivated." (PMID 19116663, 2008). "SRY mutations residing in the HMG (High Mobility Group) domains are found in 10–15% of the 46,XY gonadal dysgenesis cases and affect binding to and bending of DNA or nuclear transport." (PMID 22815844, 2012).
melanoma (6 papers, 2016 to 2025). A malignant, usually aggressive tumor composed of atypical, neoplastic melanocytes. "SRY (sex determining region Y)-box 2 (SOX2) is an embryonic stem cell transcription factor that is associated with dermal invasion of melanoma cells." (PMID 35163570, 2022). "Recent reports have revealed that MIA expression is induced by binding of SRY (sex-determining region Y)-box 10 (SOX10) to the MIA promoter region in malignant melanoma." (PMID 27050375, 2016). "Among the three validated mRNAs, we were particularly interested in the SOX10 mRNA that encodes the Sex Determining Region Y (SRY)-Box Transcription Factor 10 (SOX10), which has a well-known activity as a transcription factor regulating tumor initiation, maintenance, and progression in melanoma." (PMID 40956859, 2025). "Classically, the immunohistochemistry reveals strong positivity for melanocytic markers, such as human melanoma black 45 (HMB-45), Melan A, S100 protein, and SOX10 (SRY (Y sex determination region) - Box 10)." (PMID 40978962, 2025). "To further elucidate the inhibitory mechanism, we investigated the effect of VP on the SRY (sex determining region Y)-box 10 (SOX10) and paired box gene 3 (PAX3) transcription factors that regulate melanoma markers such as protein melan-A (MART-1) and MITF expressed in melanoma cells." (PMID 33672928, 2021).
prostate carcinoma (6 papers, 2013 to 2023). A carcinoma that arises from epithelial cells of the prostate gland. "SRY expression has also been reported in prostatic tissues, and loss of SRY and other Y-chromosome-encoded genes is a frequent finding in prostate cancer." (PMID 24681825, 2014). "Downregulation of SRY has been observed in prostate cancer, but it often occurs concurrently with the downregulation of other Y chromosome-specific genes." (PMID 38132479, 2023). "Further research is needed to elucidate the specific role of SRY and its potential contributions to prostate cancer and other cancers." (PMID 38132479, 2023). "DU145 prostate cancer cells are male in sex and therefore harbor a single copy of the SRY gene in their genome." (PMID 25030902, 2014). "In the context of cancer, particularly in prostate cancer, the role of SRY is not well understood, and it is unclear whether SRY acts as a tumor suppressor or has other implications in cancer development." (PMID 38132479, 2023). "Therefore, it would be premature to attribute the development and proliferation of prostate cancer solely to the downregulation of SRY." (PMID 38132479, 2023). "We screened 51 standard sequence tagged sites (STSs) corresponding to a male-specific region of the Y chromosome (MSY), sequenced the coding region of the SRY gene and assessed the status of the DYZ1 arrays in the human prostate cancer cell lines DU145 and LNCaP." (PMID 23663454, 2013).